INS (insulin)
Diseases named in the same sentence as INS in open-access papers (continued):
Sharing a sentence is not in itself a finding about the gene and the disease.
Hyperglycemia (continued). "GCK heterozygous LOF mutations have been associated with a reduced GCK activity that alters the glucose threshold for stimulating insulin secretion and eventually a mild form of fasting hyperglycemia present from birth and named as GCK-MODY (traditionally known as MODY2)." (PMID 35052457, 2022). "Furthermore, ablation of Sam68 in hepatocytes protects mice from high-fat diet (HFD)-induced hyperglycemia and significantly increased hepatic and peripheral insulin sensitivities." (PMID 36232770, 2022). "Chronic hyperglycemia significantly raises the polyol pathway in insulin insensitive tissues." (PMID 35276982, 2022). "It has been reported that autophagy may play a protective role by clearing the aggregates of ubiquitinated proteins resulting from hyperglycemia in insulin-expressing β cells." (PMID 36704029, 2022). "Subcutaneous regular insulin was used in all participants with DM1 during the OGTT, this likely led to the lower insulin levels and more pronounced hyperglycemia following OGTT in the DM1 group, which could impact vascular responses." (PMID 34894721, 2022). "Endogenous or exogenous insulin is less effective in poorly controlled hyperglycemia than in well-controlled patients, which might lead to severe fasting hyperglycemia, resulting in higher FPG than eAG levels." (PMID 35627961, 2022). "In addition, glucose tolerance tests showed an amelioration of hyperglycemia and increased insulin secretion at all the measured time points in subjects receiving neratinib." (PMID 35054822, 2022). "Simultaneously, there is a transient increase in insulin levels and a decrease in blood glucose levels, which are signs of rapid pancreatic β-cell destruction, followed by the rapid disappearance of insulin and the appearance of hyperglycemia." (PMID 36421377, 2022). "However, these mice were protected against T2D phenotypes of hyperglycemia and hyperinsulinemia due to improved insulin sensitivity and glucose absorption in the skeletal muscle and adipose tissues." (PMID 35055468, 2022). "Similarly, the liver-specific ablation of FoxO1 was shown to mitigate stress-induced hyperglycemia and hyperinsulinemia, indicating an improvement of systemic insulin sensitivity upon FoxO1 inactivation." (PMID 36232456, 2022). "Ghaddar and Diotel (2022) reviewed the implications of the zebrafish model of chronic hyperglycemia that could modulate insulin behavior." (PMID 35955446, 2022). "Despite the effectiveness of insulin in controlling hyperglycemia, it has limitations as patients and physicians are reluctant to intensify insulin treatment due to side effects such as hypoglycemia, weight gain, and the inconvenience of frequent injections in clinical practice." (PMID 35784534, 2022). "Moreover, IRE1 affects the biosynthesis of insulin: in hyperglycemia, it induces β cell homeostasis and thus an improvement in pro-insulin biosynthesis." (PMID 35328914, 2022). "However, considering the influence of insulin resistance in amyloid protein aggregation, the mechanisms of hyperglycemia-induced neurodegeneration remain obscure." (PMID 35255986, 2022). "On day 35, insulin treatment was started because of persisting hyperglycemia." (PMID 36542240, 2022). "Healthy pancreatic beta cells can adapt to decreased tissue insulin sensitivity and prevent the fasting hyperglycaemia by increasing insulin secretion, but under the pre-diabetic state and T2DM, the rate at which glucose enters the bloodstream exceeds the rate of glucose uptake by tissues." (PMID 35953755, 2022). "In this regard, there is a growing consensus among the scientific community that the protracted stimulation of insulin release from β-pancreatic cells under conditions of chronic hyperglycemia may contribute to their eventual exhaustion." (PMID 36076823, 2022).
Hyperglycemia (continued). "We know that a dose of insulin increased by 30% does not cause a higher incidence of hypoglycemia episodes and leads to lower postprandial glycemia, but the incidence of hyperglycemia episodes still remains unsatisfactory." (PMID 35351180, 2022). "However, during HD, most of the insulin is removed via adsorption with dialysis membrane through electrostatic and hydrophobic interactions resulting in hyperglycemia in the post-HD period." (PMID 35528010, 2022). "Nevertheless, the present study clearly demonstrated that the proposed switch method may benefit a significant number of patients even when hyperglycemia is uncontrolled with high doses and multiple injections of insulin." (PMID 35784534, 2022). "These must have interrupted insulin action on their tissues, reduced lipoprotein lipase and facilitated peripheral tissues lipolysis, which undoubtedly hastened dyslipidaemia and hyperglycemia in the sedentary rats." (PMID 36434695, 2022). "The ability of SFG to reduce hyperglycemia can be attributed to its insulin-sensitizing activity, since SFG 2.05 db/db mice displayed a better responsiveness to insulin and a better glucose disposal as evidence of a lower HOMA-IR score and a smaller AUC of 2 h OGTT compared to db/db mice." (PMID 35893259, 2022). "However, despite careful control of hyperglycemia, 25% of patients on intensive insulin treatment still presented with neuropathy at study end." (PMID 35298717, 2022). "Although the impact of insulin therapy in situations of hyperglycemia during pregnancy would depend mainly on the severity of maternal hyperglycemia, which is very effective in severe hyperglycemia and very little, if any, in women with less severe hyperglycemia such as GDM." (PMID 35480410, 2022). "As we expected, exogenous insulin therapy at diagnosis of T1D was able to control hyperglycemia." (PMID 35407396, 2022). "Consistent with our results, by improving postprandial hyperglycemia, insulin Faster Aspart may help achieve glycemic targets during hospitalization in diabetic patients with COVID-19." (PMID 36014822, 2022). "The main pathogenic factor in T2DM is the inability of insulin-sensitive tissues to respond to insulin, and in the progressive establishment of a condition of defective insulin secretion from pancreatic cells, which eventually leads to a stably elevated blood glucose level (hyperglycemia)." (PMID 35335211, 2022). "This may result in reprogramming of insulin target tissues in offspring such as liver and adipose tissue, leading to hyperglycemia in adulthood." (PMID 36733795, 2022). "Here, we report that insulin-controlled hyperglycemia slightly aggravated AD-type pathologies and cognitive impairment; however, RH significantly increased neuronal hyperactivity and accelerated the progression of cognitive deficits in streptozotocin-induced (STZ-induced) diabetic APP/PS1 mice." (PMID 35077394, 2022). "These mice developed fasting hyperglycemia, glucose intolerance, and reduced insulin sensitivity." (PMID 36430706, 2022). "Alternative methods to consider may be assessment of the beta-cell mass by both acute insulin response to arginine at hyperglycemia (AIRmax), as a correlate of beta-cell mass, and beta-cell function by (IvGTT)." (PMID 34983671, 2022). "After LSG, ghrelin reduction may be important in the prevention of weight regain, with ghrelin shown to have diabetogenic effects by suppressing insulin secretion and possibly inducing hyperglycemia." (PMID 36554054, 2022). "Thus, our results indicated that saroglitazar (2 and 4 mg/kg/day, PO) treatment improved insulin sensitivity in adipose tissue, and decreased hyperglycemia and hyperinsulinemia in MSG-obese Wistar rats." (PMID 36033946, 2022). "Notably, hyperglycemia can increase Insr expression in lymphocyte and cancer cell lines, while high glucose inhibits β‐cell Insr expression through autocrine insulin action and INSR‐FOXO1 signaling." (PMID 34921686, 2022).
Hyperglycemia (continued). "β-cell viability and insulin release could be crippled as a consequence of hyperglycaemia and glucotoxicity in human body." (PMID 36045734, 2022). "DM is characterized by hyperglycemia that occurs due to the impairment of absolute insulin function because of the autoimmune destruction of pancreatic beta cells (Type 1) and relative insulin function due to a combination of impaired pancreatic beta-cell function with insulin resistance (Type 2)." (PMID 36035647, 2022). "As a consequence of pancreatic agenesis/hypoplasia, these patients not only require insulin as the treatment of choice for hyperglycemia but may also need pancreatic enzyme supplementation." (PMID 35052457, 2022). "Therefore, in addition to insulin alone, multitargeted therapy is critical for the treatment of stress hyperglycemia." (PMID 35784538, 2022). "One exception is when a GCK‐MODY affected pregnant woman carries an unaffected fetus (i.e., fetus without maternal GCK mutation), when insulin treatment of maternal hyperglycemia is recommended." (PMID 36483860, 2022). "The pathogenesis of hyperglycemia is linked to muscle insulin resistance as opposed to hepatic insulin resistance." (PMID 36060389, 2022). "Like neural cells, vascular endothelial cells are sensitive to hyperglycemia as glucose uptake is independent of insulin, increasing the risk of cytotoxicity." (PMID 34991588, 2022). "The intermittent or real-time use of CGM may help to manage postprandial hyperglycemia better and suggest a more effective insulin formulation." (PMID 36014822, 2022). "Hyperglycemia and hypertriglycemia increase oxidative stress, increased BMI will increase adipokines, antidiabetic medicines (such as sulfonylurea and insulin), contribute to the elevated insulin level, and subsequently stimulate mitogenic pathways." (PMID 35299970, 2022). "A possible explanation could be related to an enhanced stimulation of the endocrine pancreas by the post‐feeding hyperglycemia due to the impaired insulin responsiveness after glucose administration." (PMID 35986504, 2022). "Given its insulin-lowering effects, the use of metformin to prevent and/or treat alpelisib-induced hyperglycemia may also enhance the anticancer effects of alpelisib." (PMID 35406370, 2022). "However, a more recent study recommended using 100% to 150% correction based on a patient’s usual insulin correction factor to prevent post-HIIT hyperglycemia." (PMID 35345701, 2022). "Once potentially treatable causes have been ruled out, hyperglycemia is treated by lowering the glucose infusion rate and administering insulin, though the latter increases the risk of hypoglycemia." (PMID 36290668, 2022). "We investigated the association of insulin administration method with the achievement of mean glucose ≤ 180 mg/dL and neurological outcomes in out-of-hospital cardiac arrest (OHCA) survivors who had hyperglycemia after the return of spontaneous circulation." (PMID 36584121, 2022). "Finally, hyperglycemia due to insulin insensitivity helps to further promote the growth of metabolically active tissues, including endometrial hyperplasia and cancer." (PMID 35615721, 2022). "Therefore, therapy with insulin in patients with liver cirrhosis requires close monitoring of blood glucose levels to avoid the risks of hypoglycemia or hyperglycemia." (PMID 35252271, 2022). "However, the majority of the m.3243A > G carriers had abnormal glucose tolerance compared with the normal glucose-tolerant healthy controls, and so a confounding effect of hyperglycemia on insulin sensitivity cannot be excluded." (PMID 35552684, 2022). "Perhaps these effects could explain the improvement of hyperglycemia, hyperinsulinemia, and insulin sensitivity in the EA group." (PMID 36233611, 2022).
Hyperglycemia (continued). "The pathogenesis of this microvascular complication is complex and not completely known, involving several alterations among which hyperglycemia and insulin resistance play particularly central roles leading to oxidative stress, inflammatory activation and altered barrier function of endothelium." (PMID 36140374, 2022). "Notably, MG53-exaggrated hyperglycemia and insulin insensitivity were much more severe in db/db mice at 12 weeks of age relative to the younger group (8-week-old)." (PMID 36337049, 2022). "Use of insulin to correct hyperglycemia may be needed before exercise in patients with blood glucose higher than 350 mg/dL." (PMID 35345701, 2022). "Additionally, stress-induced hyperglycemia is considered to be due to pancreatic failure to compensate for increasing insulin production and release." (PMID 35273920, 2022). "Insulin stimulated by hyperglycemia could modulate the gonadotropin-releasing hormone (GnRH) receptors and increase LH secretion, and insulin and LH enhanced corpus luteum steroidogenesis with progesterone secretion." (PMID 35743808, 2022). "Therefore, reducing postprandial hyperglycemia and slowing glucose absorption by inhibiting α-glucosidase is another therapeutic approach to restoring insulin sensitivity." (PMID 36080485, 2022). "The rise of insulin blood level and weakening of hyperglycemia, observed in APH-treated diabetic rats, are in suitable agreement with an increase in the mass and functional activity of extra-islet IPCs and, in part, may be linked." (PMID 35457103, 2022). "Our results confirmed that a high level of insulin and hyperglycemia decreases AMPK activity through phosphorylation of AMPK subunits by the PI3K/AKT pathway, where the protein levels of AMPK and PI3K/AKT were downregulated after 30 min of renal ischemia and 48 h reperfusion." (PMID 35688972, 2022). "Only one patient, receiving steroids, required insulin therapy due to hyperglycemia." (PMID 35288599, 2022). "However, if the demand for insulin is too high, the phenomenon of glucotoxicity occurs, resulting in the overburdening and dysfunction of the β-cells that leads to hyperglycemia." (PMID 36077491, 2022). "However, our STZ-treated diabetic control group represented a much more severe phenotype compared with patients with T1D who receive insulin therapy, because these mice experience chronic untreated hyperglycemia." (PMID 35015736, 2022). "In addition, the combination of elevated plasma glucose levels (hyperglycemia) and high insulin concentrations (hyperinsulinemia) promote hepatic de novo FA lipogenesis and impair β-oxidation, thereby contributing to the development of hepatic steatosis." (PMID 35805898, 2022). "In addition, it was reported that smoking, HT, hyperglycemia, DM, elevated HbA1c, insulin use, alcohol intake, total cholesterol, and LDL-chol are involved in the severity of DR and arteriosclerosis." (PMID 36078984, 2022). "For persistent GC-induced hyperglycemia, basal-bolus insulin therapy is recommended." (PMID 34986826, 2022). "Therefore, the present findings in this study were consistent with earlier work from our lab as well as other studies that have shown hyperglycemia and altered insulin secretion in HFD/STZ-induced animals." (PMID 36359384, 2022). "The EMERGE trial will determine whether early routine use of metformin reduces the need for insulin use or hyperglycaemia and reduces excessive maternal weight gain, maternal and neonatal morbidities and the cost of treatment for women with GDM." (PMID 36131291, 2022). "Intravenous insulin therapy has been a standard of care for hyperglycemia." (PMID 35959169, 2022). "Similarly, siRNA knockdown of eIF5A prevented hyperglycemia and maintained insulin secretory capacity in mice treated with low doses of streptozotocin to induce β-cell damage." (PMID 35448531, 2022).
Hyperglycemia (continued). "We suggest that these mice have reduced insulin sensitivity (hyperglycemia) and as a compensatory mechanism there is overactivation/expression of insulin receptor in the brain rendering neuronal circuits resistant to seizure induction after injection of insulin." (PMID 35264925, 2022). "Trehalose is not synthesized in the human body but is formed in many other organisms ranging from bacteria to plants; this compound may modulate insulin sensitivity via more than seven molecular pathways, thereby leading to better control of hyperglycemia." (PMID 35330193, 2022). "Also, PDX1-expressing MSCs can transform into β-like cells which produce insulin after transplantation in vivo, display glucose-stimulated insulin secretion, and reduce hyperglycemia in diabetic mice." (PMID 35883121, 2022). "An upregulation of ALDOB in human pancreatic β cells occurs upon the development of hyperglycemia and may contribute to the impairment of insulin secretion in humans." (PMID 35230239, 2022). "However, because of insufficient response, ketoconazole treatment was discontinued, and the dose of pasireotide treatment was increased, and hyperglycemia was controlled with insulin and oral antidiabetic agents." (PMID 36161631, 2022). "Importantly, the insulin therapy was only administered to mice in severe hyperglycaemia with BG levels over 30 mmol/L." (PMID 36339443, 2022). "Moreover, Cotadutide improved fasting plasma glucose, fructosamine, HbA1c, percentage of time in hyperglycemia, insulin secretion, and resistance." (PMID 35488292, 2022). "The higher micturition frequencies might be due to the inhibition of antidiuretic hormone release and hyperglycemia due to inhibition of insulin secretion from pancreatic beta cells." (PMID 35832332, 2022). "However, there are molecules other than cytokines in serum that can reduce insulin signaling including FFAs, lipotoxicity, hyperglycemia, and hyperinsulinemia." (PMID 36504710, 2022). "Postprandial hyperglycaemia has been described in five of 10 dogs receiving NPH insulin." (PMID 35152907, 2022). "However, data are limited concerning the effects of carbohydrate loading on preoperative hyperglycemia and insulin management in patients with ovarian cancer patients previous to interval cytoreductive surgery." (PMID 35197061, 2022). "In mammals, glucose sensing in the EECs is a main mechanism by which insulin secretion is regulated, since the combined actions of the incretin hormones GLP-1 and GIP, both released from EECs upon the ingestion of glucose, potentiate hyperglycemia-induced insulin secretion." (PMID 35121731, 2022). "The analysis of PHLPP phosphatases mRNA expression showed that prolonged insulin stimulation of HEC-1A cells caused both in hypoglycemia and hyperglycemia conditions to a decrease in PHLPP1 and increase in PHLPP2 after 4 h stimulation and then the level was similar to in control cells." (PMID 36497428, 2022). "When exploring the data from the individual mice, we found that the long-term hyperglycemia, calculated as the AUC of the glucose curves during the 8-week study, negatively correlated to the percentage of insulin+ cells and positively correlated with the percentage of glucagon+ cells." (PMID 35203411, 2022). "This is typically ascribed to increased insulin production by the fetal pancreas in response to maternal hyperglycemia, although transplacental insulin passage may contribute." (PMID 35197933, 2022). "We demonstrated that MEP could affect hyperglycemia, insulin sensitivity, dyslipidemia, immunomodulation, and modulate gut microbiota." (PMID 36276816, 2022). "Chronic hypercortisolism leads to hyperglycemia through several mechanisms that include exacerbation of the liver gluconeogenesis, reduction of glycogen synthesis, decrease in insulin sensitivity and β-cell function in the pancreas, and impairment of the glucose uptake to the muscle." (PMID 34988348, 2022).